CDK19 (cyclin dependent kinase 19)
Diseases named in the same sentence as CDK19 in open-access papers (continued):
Sharing a sentence is not in itself a finding about the gene and the disease.
cancer (36 papers, 2013 to 2025). A tumor composed of atypical neoplastic, often pleomorphic cells that invade other tissues. "These isoforms were upregulated in Clusters A and C. This group contains two isoforms of CDK19, a gene implicated in cancer proliferation (a third isoform, CDK19-203, lacks the seventh exon and decreases in metastatic samples)." (PMID 35560144, 2022). "We presented the mutations of CDK19 and addressed the relation of CDK19 expression with immune cell infiltration by means of the cBioPortal, Catalogue of Somatic Mutations in Cancer (COSMIC) and Tumor IMmune Estimation Resource (TIMER) databases." (PMID 34649520, 2021). "CDK8 and CDK19 Mediator kinases are transcriptional co-regulators implicated in several types of cancer." (PMID 31382571, 2019). "Activities of CDK8 and CDK19 have been implicated in sustained proliferation and viability of cancer cell lines, probably by modulation of various gene expression programs." (PMID 28422713, 2017). "In contrast to CDK8, almost nothing is known about CDK19 roles in cancer, and whether it compensates for loss of CDK8 remains unknown." (PMID 36545778, 2023). "A number of small-molecule CDK8/CDK19 inhibitors have been developed and their anti-cancer effects demonstrated in preclinical studies of multiple tumour types." (PMID 40163908, 2025). "CDK8/CDK19 inhibitors can also enhance anti-tumour immunity, with current evidence suggesting that they act primarily in a cancer cell-extrinsic manner." (PMID 40163908, 2025). "CDK19 that activates proliferation of hematopoietic and potential cancer stem cells are downregulated by 433‐3β." (PMID 40007440, 2025). "A pan-cancer analysis using TCGA data revealed exceptionally high CDK19 expression in PC, correlating with disease progression and aggressive features, such as higher Gleason scores and advanced stages." (PMID 40361480, 2025). "Mediator kinases show remarkable clinical correlations in PCa, the only type of cancer marked by high CDK19 expression in primary tumors." (PMID 38546787, 2024). "CDK19 expression further increases in PCa, reaching higher levels than in any other cancers; in contrast, CDK19 greatly decreases during testicular carcinogenesis." (PMID 38546787, 2024). "We have also determined CDK8/CDK19 RNA ratios in the same cell lines using our RNA-Seq data for 293 cells and RNA-Seq data of Cancer Cell Line Encyclopedia (CCLE) for all the other cell lines." (PMID 37378433, 2023). "Cyclin-dependent kinase 19 (CDK19) is an important regulator in the process of cancer, and CDK19 inhibitors can be used as a kinase inhibitor for cancer treatment." (PMID 35451651, 2022). "Analysis of CDK8/CDK19/CCNC alterations identified several cancer subtypes where these genes were frequently altered." (PMID 31382571, 2019). "To facilitate this analysis, we identified a cancer cell line (SJSA) that is naturally depleted of CDK8 protein but retains CDK19." (PMID 28416637, 2017). "Treating these mice with prototype CDK8/19 drugs inhibited the activity of CDK8 and CDK19 in the cancer cells and slowed the growth of colorectal tumors." (PMID 27935476, 2016). "Therefore, combining with Treg inhibition might improve the therapeutic effect of Cdk8/Cdk19 inhibitors in cancer therapy." (PMID 31552016, 2019). "Although our findings do not rule out other possible contributions of CA mechanisms, we found that CA-mediated modulation of CDK19 is sufficient to inhibit YAP-induced cellular O-GlcNAcylation and proliferation under HG conditions in a cancer model." (PMID 34588426, 2021). "CDK19 and its paralog CDK8 are known to promote different cancer-related pathways in several solid tumors, such as TGF-β/BMP-induced epithelial–mesenchymal-transition (EMT), and NFκB-mediated gene transcription." (PMID 32752128, 2020). "Our findings identify CDK19 as a potential biomarker in HNSCC to predict recurrent disease and support recent developments to target CDK19 and its paralog CDK8 in advanced cancer." (PMID 32752128, 2020).
cancer (continued). "Examination of alterations in different cancers shows that CDK8, CDK19 and CCNC can be amplified or deleted either independently of each other or in combinations." (PMID 31382571, 2019). "Western blot analyses of multiple cancer cell types revealed that most express both CDK8 and CDK19 protein." (PMID 28416637, 2017). "The analysis of Mediator kinase expression in clinical cancers, together with prior reports, shows that CDK8 is downregulated and CDK19 upregulated in primary PCa, which we can now explain by the regulation of CDK8 and CDK19 expression by androgen signaling." (PMID 38546787, 2024). "Cancer Cell Line Encyclopedia (CCLE) data analysis showed that RNA expression of CDK8 (but not of CDK19 or CCNC) was significantly higher in TNBC cell lines than in cell lines from other subtypes of BrCa." (PMID 39541354, 2024). "Recently, CDK19 and CDK8 emerged as promising potential therapeutic targets in cancer therapy." (PMID 32752128, 2020). "Consistent with previous data in other tumor types, our study indicated that CDK19 might contribute to HNSCC progression and aggressiveness, supporting recent developments to target CDK19 and its paralog CDK8 in advanced cancer." (PMID 32752128, 2020). "To identify other cancers where these novel drugs may provide benefit, we queried genomic and transcriptomic databases for potential impact of CDK8, CDK19, or their binding partner CCNC." (PMID 31382571, 2019). "CKD8-dependent gene expression of glycolytic genes was shown to be conserved among 25 different cancer cell lines and independent of CDK19." (PMID 30693281, 2018). "Pharmacological inhibition of CDK8 and CDK19 by the steroidal alkaloid Cortistatin A (CA), deregulates expression of tumor suppressors and lineage-controlling genes in AML and results in suppressed growth of cancer cells." (PMID 28422713, 2017). "In an effort to better delineate CDK19-specific roles from potential redundant functions of CDK8, we screened cancer cell lines to assess whether any might serve as a useful “model system” to study CDK19." (PMID 28416637, 2017). "Interestingly, we showed that CDK19 is upregulated by TRIM44 siRNAs in a pluripotent human testicular embryonic cancer cell line, suggesting that TRIM44 also plays a tumor-promoting role in the pathogenesis of other types of cancer by modulating CDK19 expression." (PMID 28885545, 2017). "Whereas CDK19 and CDK20 are not essential in any of the cancer cell lines tested, there is a minor proportion of cell lines in which CDK8 (~ 3%), CDK10 (~ 1%), CDK12 (~ 27%) and CDK13 (~ 3%) are essential." (PMID 36577800, 2022). "Thus, despite their established roles as regulators of Mediator, and considerable interest in their therapeutic targeting in cancer, we do not yet fully understand the redundant and specific roles of CDK8 and CDK19." (PMID 36545778, 2023).
tumor (30 papers, 2015 to 2025). "A recent study showed that CDK8/CDK19 inhibition reversed the castration-resistant phenotype of CRPC tumours in vivo by modifying the oncogenic transcriptional responses to castration." (PMID 40163908, 2025). "Similar to the in vitro molecular biomarkerdata, the tumor STAT1SER727 phosphorylation data indicatea partial redundancy between CDK8 and CDK19 loss, with CDK8 inhibitionplaying a greater role than CDK19 in the molecular response to CCT251921treatment in vivo." (PMID 40601435, 2025). "In natural killer (NK) cells, CDK8/CDK19 inhibition augments production of key cytolytic molecules to increase tumour kill and enhance response to anti-PD-1 immunotherapy." (PMID 40163908, 2025). "Analysis of CDK8 and CDK19 gene expression in 4,798 normal and 7,843 tumor tissue clinical samples from 16 different organs was conducted using RNA-Seq data in the TNMplot database." (PMID 38546787, 2024). "Among genes with the highest differential expression between p63pos and p63neg ACC we shortlisted the proliferation marker MKI67 and the cyclin dependent kinase CDK19, both highly upregulated in p63neg tumor (FC > 1.2, FDR < 0.05, p < 0.001)." (PMID 36720951, 2023). "Herein, we found that miR-222-3p acted as a tumor-suppressor to inhibit OC cell migration and proliferation in vitro, and inhibit tumor metastasis and growth by targeting CDK19, revealing the significance of miR-222-3p and CDK19 in OC." (PMID 35451651, 2022). "We found that STZ induced CDK19 expression in transplanted tumor tissue, while CA reduced the increase in CDK19 expression induced by STZ." (PMID 34588426, 2021). "The relationships between 6 immune cell types (B cells, CD8 + T cells, CD4 + T cells, macrophages, neutrophils and myeloid dendritic cells) and CDK19 expression were determined by Spearman tests (tumor purity adjusted)." (PMID 34649520, 2021). "Based on these observations, CDK19 emerged as a promising therapeutic target in different tumor types, leading to the development of small-molecule inhibitors impeding the activity of CDK19 and its paralog CDK8." (PMID 32752128, 2020). "STAT1 is known to be immunomodulatory and is associated with PD-L1, indicating a potential effect of CDK19 on tumor immune microenvironment." (PMID 32752128, 2020). "In contrast to most targets of tumor-suppressive drugs (such as, for example, CDK4/6), very few tumor cell lines showed pronounced dependency on CDK8/CDK19/CCNC in DepMap analysis." (PMID 31382571, 2019). "Additionally, prolonged CDK8/CDK19 inhibition downregulated the MYC pathway leading to tumour regression." (PMID 40163908, 2025). "Inhibition of CDK8/CDK19 was shown to influence gene expression in host stroma of mice harbouring CRPC xenografts and these transcriptional changes were tentatively linked to tumour suppression." (PMID 40163908, 2025). "Restoration of CDK19 expression reversed the inhibition of tumor growth by miR-222-3p." (PMID 35451651, 2022). "Besides, we observed that miR-222-3p directly binds to the 3′-UTR of CDK19 and inhibits CDK19 translation, thus inhibiting OC cell migration and proliferation in vitro and repressed tumor growth in vivo." (PMID 35451651, 2022). "Moreover, H&E staining revealed lower stroma-rich architecture in tumor tissues in the LV-miR-222-3p and CDK19 co-transfected group compared with the LV-miR-ctrl OE-CDK19 co-transfected group." (PMID 35451651, 2022). "Further research indicated that the mediator kinase CDK19 was closely related to tumor migration." (PMID 35451651, 2022).
tumor (continued). "In particular, cell cycle genes such as CSNK2A1, MCM8, CDK19, KIFC1 and MCM7, among which KIFC1 was previously found to be a factor for poor prognostic and a therapeutic target associated with tumour proliferation in HCC34,35, even though its immunodulatory function has never been described before." (PMID 33431814, 2021). "Moreover, CDK18/CDK19 inhibition suppressed the tumour-promoting activities of fibroblasts and decreased intra-tumoural blood supply in an AR-driven patient-derived xenograft model, the latter finding suggesting that these kinases enhance tumour angiogenesis." (PMID 40163908, 2025). "The IHC staining of the tumor of mice showed that the expression of CDK19 protein was significantly increased in the LV-miR-ctrl and OE-CDK19 co-transfected group, while the expression of CDK19 protein was reversed in the LV-miR-222-3p and CDK19 co-transfected group." (PMID 35451651, 2022). "Therefore, cyclin C/CDK3/CDK8/CDK19 complexes function as tumor suppressors in T-ALL by preventing the accumulation of ICN1 and the lack of these complexes led to enhanced T-ALL development in Lck-LMO1 transgenic mice that mimic the alterations found in human T-ALL." (PMID 25914884, 2015). "Therefore, because of the dual role of the cyclin C/CDK8/CDK19 complexes functioning in some tumors as oncogenes and in other tumors as tumor suppressor genes the use of pharmacological inhibitors of this complex should be carefully considered depending on tissue type." (PMID 25914884, 2015). "Truncation of the long 3'UTR of Cdk19 recapitulates cholesterol biosynthesis and proliferative impairments, as well as the enhanced anti-tumor CD8+ T cell activity observed upon NUDT21 depletion, whereas CDK19 overexpression rescues these phenotypes." (PMID 41255211, 2025). "To understand the role of Mediator kinases in CRPC, we analyzed their effects on transcription and tumor growth using both mutagenesis of CDK8 and CDK19 and pharmacological inhibition of Mediator kinases in 22Rv1, a “classical” androgen-independent CRPC model." (PMID 38546787, 2024). "Meanwhile, on the TCGA portal, we found that CDK7, CDK8, CDK9, CDK12, CDK19, and CDK20 mRNA levels were differentially expressed in the 4 molecular tumor subtypes." (PMID 33686962, 2021). "Inhibition of CDK8/CDK19 by Senexin B or knockdown counteracts the signal rewiring of EMT-promoting factors and tumor cell invasion." (PMID 31248103, 2019). "We have also used cBioPortal to query RNA-Seq data for CDK8, CDK19, and CCNC RNA expression in different tumor types in the TCGA data." (PMID 31382571, 2019). "We investigated the effects of CDK8 and CDK19 expression and kinase activity on in vivo growth of 22Rv1 xenografts, with or without androgen deprivation, by monitoring tumor growth of 22Rv1 derivatives in intact or castrated male NSG mice." (PMID 38546787, 2024). "Studies have shown that CA can reduce the O‐GlcNAcylation of YAP by inhibiting cyclin‐dependent kinase 19 (CDK19), which means that CA may reverse the function of O‐GlcNAcylated YAP on the tumor inhibition effect of pVHL." (PMID 37576865, 2023). "A combination of Senexin B (a CDK8/CDK19 inhibitor) with fulvestrant (a selective down-regulator of the estrogen receptor) shows an enhanced tumor-suppressive effect with no apparent toxicity in mouse models." (PMID 31248103, 2019). "Thus, after high expression in cases of human PC being reported, the cyclin-dependent kinase 19 (CDK19) was identified as a specific and sensitive biomarker for the diagnosis of high-grade PIN, reflecting its involvement in the progression of neoplastic disease, as well as its malignant potential." (PMID 35681707, 2022).
tumor (continued). "Interestingly, expression of CDK19 and CDK20, which did not appear to influence cell survival in the in vitro conditions used to generate the DepMap dataset, are nonetheless associated with better/worse tumor progression free survival (PFS) in multiple tumor types." (PMID 36577800, 2022). "The vast majority of genes were equally expressed in tumor and non-tumoral, control pituitary glands, including CCNL1, CCNE2, CCNB2, CCNA1, CDK18, CDK19 and CDK20." (PMID 35260162, 2022). "As our data suggest that tumor-intrinsic CDK8 controls NK-cell immune evasion in a kinase-independent manner, CDK8/CDK19 kinase inhibitors would not suffice to reach a clinical benefit." (PMID 34689158, 2021).
infection (1 paper, 2020). The state of being infected such as from the introduction of a foreign agent such as serum, vaccine, antigenic substance or organism. "Chemical inhibition of CDK8 and CDK19 with Senexin A during infection blocks virus-induced expression of select metabolic and autophagic genes, hexokinase 2 (HK2) and microtubule-associated protein 1 light chain 3 (LC3), and reduces viral genome replication and infectious particle production." (PMID 32560467, 2020). "This suggests only that CDK19 levels do not need to be increased to support DENV2 replication, as opposed to the clear association of infection with increased CDK8." (PMID 32560467, 2020).
CDK19 also shares sentences with these, for which no sentence is quoted: acute lymphoblastic leukemia (2 papers); colorectal cancer (2); cervical carcinoma (1); chronic myeloid leukemia (1); colon adenocarcinoma (1); colon carcinoma (1); dementia (1); dengue virus infection (1); developmental and epileptic encephalopathy, 87 (1); diabetes (1); fibrosarcoma (1); genetic diseases (1); graft-vs.-host disease (1); hematologic malignancies (1); inflammatory bowel disease (1); kidney cancer (1); liposarcoma (1); nervous (1); neurodevelopmental disorder (1); Nystagmus (1); Obesity (1); osteochondropathies (1); prostate tumors (1); rectal adenocarcinoma (1); rheumatoid arthritis (1); stomach adenocarcinoma (1); T-cell acute lymphocytic leukemia (1); tubular stomach adenocarcinoma (1).